IL33 (interleukin 33)
Diseases named in the same sentence as IL33 in open-access papers (continued):
Sharing a sentence is not in itself a finding about the gene and the disease.
eosinophilia (continued). "However, several other inflammatory pathways have been shown to support eosinophilia, including IL-13, and most recently, the alarmin cytokines TSLP and IL-33." (PMID 33917396, 2021). "The expression of CCL11, CCL24, and IL33 increased significantly in mice treated with PPE alone, which may contribute to PPE-induced eosinophilia in the lung." (PMID 34950055, 2021). "Importantly, STAT6–/– x IL5Tg or IL4Rα–/– x IL5Tg mice had comparable blood eosinophilia, and ILC2 expansion after IL-33 treatment was equivalent." (PMID 33974563, 2021). "However, several other inflammatory pathways have been shown to support eosinophilia, including IL-13, the alarmin cytokines TSLP and IL-33, and the IL-3/5/GM-CSF axis." (PMID 33917396, 2021). "In wild-type mice, IL-33 induced marked eosinophilia in BALF (non-treated vs. IL-33-treated: 0.0% vs. 35.7 ± 8.1%; p < 0.001)." (PMID 34074279, 2021). "The cytokine IL-5 promotes eosinophilic inflammation, and we have previously shown that ILC2s and not TH cells produce IL-5 locally in the bone marrow in IL-33-driven eosinophilia." (PMID 32466530, 2020). "In contrast, IL-33-induced bone marrow and airway eosinophilia were abolished in the absence of ILC2s in Rag2−/−Il2rg−/− mice and no production of IL-5 was detected in IL-33-stimulated bone marrow cultures." (PMID 32582171, 2020). "In animal studies, IL-33 knockout mice did not develop lung eosinophilia after allergen induction, which suggests that IL-33 is essential for eosinophilic infiltration." (PMID 30386455, 2018). "Our findings show for the first time that increased expression of IL-33 and its receptor ST2 is associated with airway eosinophilia in non-atopic COPD patients." (PMID 29859068, 2018). "We also demonstrated that NJ.1638 mice had diminished eosinophils in the absence of ST2, indicating that IL-33 regulated the capacity of IL-5 to drive eosinophilia." (PMID 28512632, 2017). "We found that IL-33-treatedanimals showed lower number of total cells and neutrophils in BALF when compared to non-treated TB group and surprisingly IL-33 did not induce eosinophilia." (PMID 28128217, 2017). "In addition to activating ILC2s, IL-33 activates lung DCs via OX40L upregulation to promote Th2 differentiation of naïve lymphocytes and exacerbates eosinophilia." (PMID 26473724, 2015). "The potential of IL-33 to promote IL-548, 49 and CCL248 release could contribute to this observed eosinophilia." (PMID 24636086, 2014). "Although both IL-33 and IL-25 were produced by the nasal epithelial cells, we found that the IL-33—but not the IL-25—derived from those cells was crucial for eosinophilia and goblet cell hyperplasia, without affecting Th2 cell development." (PMID 24205109, 2013). "Even though they may not be pathognomonic for CRS, elevated blood eosinophilia and IL-33, along with other cytokines’ overexpression, may allow the assessment of tissue remodeling in the chronic processes of paranasal sinuses." (PMID 38137606, 2023). "As with IL-33 activation, ILC2 expansion was reduced in the absence of either amino acid transporter following helminth infection, and associated with trends toward reduced eosinophilia, although these failed to reach statistical significance." (PMID 36571761, 2023). "We hypothesize that BM ILC2s are an essential factor for RA disease initiation, and subsequent IL-33-induced ILC2s production is regulated through a negative feedback loop, leading to the peripheral eosinophilia, including rEOS accumulation in joint." (PMID 36181091, 2022). "Eosinophilia was sharply reduced by Hp‐TGM co‐administration, indicating direct effect(s) on innate cell populations, together with overall diminution of type 2 cytokines, in particular BALF IL‐5 and lung IL‐33, the latter known to be an essential driver of immune responses in this model." (PMID 35758054, 2022). "However, in ob/ob mice, IL-33 did not induce significant eosinophilia (non-treated vs. IL-33-treated: 0.0% vs. 2.9 ± 1.2%)." (PMID 34074279, 2021).
eosinophilia (continued). "Nonetheless, it is tempting to speculate that increased levels of IL-33, produced by airway epithelial cells upon respiratory viral infection, and stronger activation of Th2 cells and ILC2, would enhance asthmic features, including BHR and eosinophilia." (PMID 34868033, 2021). "To determine whether IL-33-induced eosinophilia can develop in the absence of ILC2s, we challenged naïve lymphocyte deficient Rag2−/−Il2rg−/− mice with rmIL-33." (PMID 32582171, 2020). "However, the functional implication of IL-33-responsive ILC2s in the development of eosinophilia was not addressed in their study." (PMID 32582171, 2020). "Instead of the canonical neutrophilic response seen in wild-type infection, IL-33 treatment shifted the myeloid compartment toward dominant eosinophilia by day 2 post infection (57% with IL-33 vs. 20% without) and a trend toward increased numbers of eosinophils." (PMID 31221971, 2019). "Following challenge with IL-25, IL-33, or allergens such as Alternaria and house dust mite (HDM), pulmonary ILC2s rapidly produce copious amounts of interleukin (IL)-5 and IL-13, which in turn leads to eosinophilia and mucous production and ultimately development of AHR." (PMID 31620118, 2019). "Similarly to the serum findings, IL-33 sputum levels were significantly higher in COPD subjects with sputum eosinophilia (22.72 ± 7.42 pg/ml) than in those without (1.13 ± 0.56 pg/ml; p < 0.001)." (PMID 29859068, 2018). "That eosinophilia induction is mediated by IL-33-stimulated ILC2s and basophils, but not T cells." (PMID 30356086, 2018). "However, a negative impact was observed on IL-33-induced ILC2 accumulation and cytokine production and the associated eosinophilia in the BAL fluid of mice." (PMID 29250067, 2017). "In addition, nasal epithelial cell-produced IL-33, rather than IL-25, was important for induction of local inflammation—such as eosinophilia and goblet cell hyperplasia—in HDM-induced AR." (PMID 24205109, 2013). "In addition to IFN and IL pathways known to signal through the JAK/STAT pathway, Reactome analysis revealed enrichment of leukotriene/eoxin and IL-33 signaling, suggesting unexpected mechanisms by which enhanced JAK1 signaling may drive allergic inflammation and eosinophilia." (PMID 36546480, 2022). "However, blocking ICAM-2 in vivo during IL-33-induced airway inflammation did not affect either the numbers of pulmonary ILC2s or BAL eosinophilia, suggesting that ICAM-2 — either on ILC2s or other cells — does not affect ILC2 accumulation in the lungs, at least sufficiently." (PMID 33193309, 2020). "Thus, in the current study we sought to assess the role of ILC2s in the regulation of allergen- and IL-33-induced bone marrow eosinophilia utilizing wild type (WT) mice, Rag1−/− mice lacking mature T and B cells but retain ILCs, and mice lacking all lymphocytes (Rag2−/−Il2rg−/−)." (PMID 32582171, 2020). "Treatment of IL5Tg mice with IL-33, but not IL-25 or TSLP, also induced a synergistic increase in bronchoalveolar lavage (BAL) eosinophilia." (PMID 33974563, 2021). "Our observations of increased Th1 (TNFα) and Th2 (IL-5, IL-33) cytokine concentrations in the BALF of dams fed a high fat diet, without any neutrophilia or eosinophilia suggest that these mice are ‘poised’ to react to further allergenic or viral exposure." (PMID 30700289, 2019). "This aspect could explain the absence of blood eosinophilia in COPD and EoE during dupilumab treatment, as the IL‐33/ST2 axis may bypass the effects of IL‐4/IL‐13 inhibition." (PMID 40492692, 2025). "Whereas IL-33, IL-25 and thymic stromal lymphopoietin (TSLP) are involved in induction of FAP-induced ILC-mediated airway eosinophilia, IL-33—rather than IL-25 and/or TSLP—was critical for the eosinophilia in our model." (PMID 30575775, 2018).
eosinophilia (continued). "Although a direct correlation has not yet been established between eosinophilia and fibrosis in the SAMP model of chronic intestinal inflammation, preliminary studies have demonstrated that IL-33 represents a critical factor important in the development of both processes." (PMID 23062310, 2012).
Obesity (111 papers, 2011 to 2025). Accumulation of substantial excess body fat. "In fact, IL-33 plays an important role in several liver diseases, including obesity-associated HCC88." (PMID 40579434, 2025). "Traditionally linked to allergic conditions, IL‐33 has recently been recognized for its role in various chronic diseases such as obesity, osteoarthritis, and diabetes." (PMID 39465143, 2024). "Obesity-associated reductions in IL-33 expression in VAT impair the function of Tregs and dysregulate the immune response, leading to an increased susceptibility to developing T2DM." (PMID 39335642, 2024). "A comprehensive understanding of IL-33’s role in immune regulation and metabolism is critical for harnessing it as a therapeutic target to manage obesity and mitigate cancer risk." (PMID 40236667, 2024). "This review will explore the various functions of IL-33 in the inflammation linked to obesity and its relationship with cancer." (PMID 40236667, 2024). "Overweight/obesity was also linked to increased plasma levels of IL-5, IL-17A, IL-22, IL-33, TNF-α, and leptin and decreased levels of IL-10." (PMID 39902293, 2024). "In this context, IL-33 acts to modulate inflammation associated with obesity and to limit adiposity by increasing caloric expenditure." (PMID 36768322, 2023). "A recent study demonstrated that Gasdermin D-mediated release of IL-33 from senescent hepatic stellate cells facilitates obesity-associated HCC." (PMID 37481543, 2023). "Obesity is also associated with the loss of IL-33-expressing MSCs, which affects not only Treg cells but also ILC2s." (PMID 34837070, 2022). "We intraperitoneally (i.p.)injected leptin receptor-deficient (db/db) obesity model mice with phosphate-buffered saline (PBS) or 0.5 μg of recombinant IL-33 (rIL-33) to activate ILC2s for 5 consecutive days." (PMID 36109558, 2022). "In any case, our results suggested that the notion that IL-33 was always beneficial in the metabolic diseases was naïve and provide a validation for an association between IL-33 serum level and obesity metabolic phenotypes in Chinese population." (PMID 33541367, 2021). "IL-33 and sST2 are abundantly expressed in adipose tissues, and IL-33 levels are correlated with high BMI, suggesting an association of IL-33 with obesity and diabetes." (PMID 33608010, 2021). "Prospective longitudinal studies are needed to investigate the causal relationship of IL-33 level and development of obesity." (PMID 33541367, 2021). "Ablation of IL-33 from white adipose niche caused immune dysregulation in these niches resulting in immune dysfunction and obesity associated with increased pro-inflammatory myeloid cells." (PMID 33708206, 2021). "Multivariate regression analyses were further performed to determine the independent association between IL-33 and obesity metabolic phenotypes." (PMID 33541367, 2021). "In summary, it is the first study to demonstrate that hypothalamic myelin disruption and the upregulation of glia-derived IL-33 were associated with HFD-induced obesity." (PMID 31291887, 2019). "Although the precise mechanisms are still unclear, elevated PTX-3, RBP-4, IL-33, irisin and decreased adiponectin levels increase the risk of obesity-related metabolic disorders." (PMID 28977161, 2017). "Ozone increased ST2+ γδ T cells, indicating that these cells can be targets of IL-33, and γδ T cell deficiency reduced obesity-related increases in the response to ozone, including increases in type 2 cytokines." (PMID 27472835, 2017). "IL-33/ST2 signaling protects against obesity-associated inflammation in visceral adipose tissue (VAT) and maintains insulin sensitivity." (PMID 26549942, 2015). "Recent studies have demonstrated a protective role for IL-33 against obesity-associated inflammation, atherosclerosis and metabolic abnormalities." (PMID 24886535, 2014). "Previous murine studies have shown a protective role for IL-33 against adiposity, obesity-associated inflammation, insulin resistance and type 2 diabetes mellitus." (PMID 24886535, 2014).
Obesity (continued). "The mechanisms by which IL-33 exerts these protective effects are not fully understood, and little is known about the role of IL-33 in human obesity and its associated complications." (PMID 24886535, 2014). "The purpose of this study was to investigate the involvement of the IL-33/ST2 system in arterial wall remodeling associated with obesity." (PMID 24265755, 2013). "Our meta-analysis aimed to quantitatively assess the significance of serum IL-33 levels in individuals with obesity and T2D to determine whether there was an association with disease." (PMID 39171751, 2024). "Despite the increasing volume of research on IL-33, there remains a critical need to consolidate and critically appraise the existing evidence to bridge knowledge gaps and offer more thorough insight into the mechanisms underlying obesity and T2D." (PMID 39171751, 2024). "Besides, a hybrid cytokine IL233 with the activities of both IL-2 and IL-33 protects mice from obesity-linked diabetic nephropathy with a more significant accumulation of Tregs, ILC2s, M2 macrophages, and eosinophils in VAT." (PMID 35574038, 2022). "Some recent findings have suggested that innate limphoid cells (ILC), mostly ILC2, activated by different cytokines including IL-33, could be also involved in obesity-associated allergic airway inflammation." (PMID 36291398, 2022). "Similar to Treg cells, ILC2s are impaired through the loss of IL-33-expressing MSCs during obesity." (PMID 34837070, 2022). "However, anti-inflammatory dendritic cells, eosinophils, and ILC2s can help prevent obesity-associated IR by promoting the differentiation of Treg cells, especially the IL33/ILC2s pathway, which is beneficial for the metabolism regulation of adipose tissue." (PMID 33472506, 2021). "Interestingly, when trend analysis was performed on the association of IL-33 with different obesity phenotypes, we found that MHOO subjects with higher IL-33 levels are more likely to develop MUOO compared to HC populations under all models." (PMID 33541367, 2021). "Additionally, we explored the source of IL-33 that activates ILC2 in vivo during chronic low-grade inflammation caused by diet-induced obesity in VAT lysates by quantitative real time PCR." (PMID 32948777, 2020). "Strategies targeting the IL-33/ILC2/beiging pathway may represent a new therapeutic approach to treat obesity and obesity-associated diseases." (PMID 32765518, 2020). "The purpose of the study described herein was to examine the hypothesis that IL-33 also contributes to the effects of O3 in mice with diet-induced obesity (DIO) caused by high fat diet (HFD) feeding." (PMID 32326950, 2020). "However, little is known about the role of IL-33 in human obesity and its associated anomalies such as atherosclerosis." (PMID 24886535, 2014). "Interestingly IL-33 signaling could be referred to as the “obesity paradox,” as being overweight or obese is associated with a favorable prognosis while having increased cardiovascular risk." (PMID 36768322, 2023). "Furthermore, IL-33 plays a critical role in obesity-associated inflammation, atherosclerosis, and metabolic abnormalities, by promoting the production of T helper type 2 cytokines and polarizing macrophages toward a protective, alternatively-activated phenotype." (PMID 33946554, 2021). "We aimed to address this gap by determining IL-33 serum level and its downstream type 2 inflammatory cytokines interleukin-5 (IL-5) and interleukin-13 (IL-13) in overweight/obese population, and analyzing the specific associations between IL-33 and obesity metabolic phenotypes." (PMID 33541367, 2021). "Thus, it is possible that IL-33 upregulation in hypothalamus during chronic HFD feeding could not only act as an alarmin to modulate obesity-associated hypothalamic inflammation, but plays a detrimental role in the maintenance of myelin structure." (PMID 31291887, 2019).
Obesity (continued). "Therefore, we sought to investigate whether obesity is associated with lower circulating levels of IL-33, and whether IL-33 is associated with clinical parameters." (PMID 24886535, 2014). "Mechanistically, obesity lowers IL-33 production in VAT DCs, contributing to the diminished Treg differentiation." (PMID 38566998, 2024). "IL-33 has the potential to influence the interplay between inflammation and metabolism, a key factor in the development of T2D among individuals with obesity." (PMID 39171751, 2024). "Given the progression from obesity to T2D, understanding IL-33’s role across the spectrum of disease is crucial." (PMID 39171751, 2024). "Another study indicated IL-33's protective role in mitigating adipose tissue inflammation during obesity." (PMID 39650246, 2024). "Research indicates that IL-33 treatment can improve the inflammation and metabolic changes related to obesity." (PMID 40236667, 2024). "To further demonstrate the contribution of IL-33 to the development of obesity, we added an OA treatment group." (PMID 38632591, 2024). "Secondly, these results further suggested the complexity of IL-33 distribution in the body and its role in obesity." (PMID 38632591, 2024). "Interleukin-33 (IL-33), an emerging cytokine within the IL-1 family, assumes a pivotal function in the control of obesity." (PMID 38632591, 2024). "Given IL-33’s importance in both obesity and cancer, much remains to be explored regarding the roles of the IL-33/ST2 pathway in various types of obesity-related cancers and their responses to treatment." (PMID 40236667, 2024). "In obesity and T2D, the PD-1/PD-L1 pathway mediates the dysfunction of hypertrophic adipocytes, M2-to-M1 polarization, and IL-33 production, maintaining inflammation of WAT, and inducing systemic insulin resistance." (PMID 38612483, 2024). "Despite its increased expression in obesity, IL-33 alone cannot maintain homeostasis in obese adipose tissue." (PMID 40236667, 2024). "Some studies have found that IL-33 can improve obesity, reduce inflammation in adipose tissue, and reduce glucose metabolism disorders." (PMID 38632591, 2024). "Given its significant role in both obesity and cancer, more research is needed to fully understand IL-33’s potential in regulating obesity and decreasing cancer risk." (PMID 40236667, 2024). "Especially for obesity, IL‐33−/− mice dysfunctioned in the maintenance of adipose tissue homeostasis and accordingly increased weight and visceral adipose tissue mass after HFD feeding." (PMID 39465143, 2024). "Further studies with larger cohorts are required to assess the significance of serum IL-33 in T2D and obesity." (PMID 39171751, 2024). "Meta-analyses were conducted to compare IL-33 levels in individuals with obesity and T2D versus healthy controls (HC), and in obesity alone versus HC." (PMID 39171751, 2024). "This systematic review and meta-analysis represents the first comprehensive evaluation of reported serum IL-33 levels in individuals with obesity and T2D." (PMID 39171751, 2024). "This is in line with previous research which showed that the circulating levels of IL–33 and its expression in adipose tissue were increased in individuals with metabolic disorders and obesity." (PMID 38255771, 2024). "Research on the role of IL-33 in developing metabolic disorders such as diabetes, obesity, and cardiovascular disease has produced mixed results." (PMID 40236667, 2024). "There is insufficient evidence to indicate significant differences in IL-33 levels in individuals with T2D or obesity compared with HC." (PMID 39171751, 2024). "The results suggest a need for improved IL-33 measurement methods to reduce heterogeneity, enhancing understanding of the role of IL-33 in obesity and T2D, and informing future research and therapeutic strategies." (PMID 39171751, 2024).